CHRM3 (cholinergic receptor muscarinic 3)
Diseases named in the same sentence as CHRM3 in open-access papers (continued):
Sharing a sentence is not in itself a finding about the gene and the disease.
colon cancer (continued). "In support of this, the wide variation in identified expression levels in CHRM3 in colon cancer, specifically across a range of experimental methods and cell lines, suggests tissue localization may play a role in the observed changes." (PMID 35370785, 2022). "Likewise, several human colon cancer cell lines commonly used in biomedical research, e.g., HT-29 and H508 cells, overexpress M3R/CHRM3." (PMID 33450835, 2021). "Although over-expression of CHRM3, the gene encoding M3R, is reported in primary colon cancers, expression of M3R itself has not been studied in colon neoplasia." (PMID 28416748, 2017). "It appears that relying on CHRM3 expression underestimates the degree to which M3R itself is over-expressed; whereas we found increased CHRM3 mRNA expression in 56% of colon cancers compared to adjacent normal colon, we detected M3R protein over-expression in 86% of a larger set of tissue samples." (PMID 28416748, 2017). "Finally, although MMP1 expression was robustly increased in almost all primary colon cancers, we were unable to demonstrate a quantitative relationship between the levels of CHRM3/M3R and MMP1 expression." (PMID 28416748, 2017). "Azoxymethane-treated Chrm3-/- mice had fewer and smaller colon tumors than wild-type mice." (PMID 24694019, 2014). "Specifically, in H508 colon cancer cells which express CHRM3, lithocholytaurine (LCT) was shown to stimulate dose-dependent increases in cell proliferation up to 200% compared to control, dose-dependent inhibition of radioligand binding, and increased IP formation." (PMID 24212649, 2011). "Using H508 human colon cancer cells with high-level expression of CHRM3 we identified bile acids as CHRM3 agonists and revealed that, as with ACh, proliferative actions of bile acids require cross-talk between CHRM3 and epidermal growth factor receptors (EGFR) and post-receptor ERK1/2 activation." (PMID 24212649, 2011). "Those miRNAs might be investigated further in CHRM3 expressing right- and left-sided colon tumors." (PMID 36919835, 2023). "We discovered new colon cancer related genes including AC007952.4, NEK8, CHRM3, ANO7, B3GNT6, NEURL1, ODC1 and KCNMA1." (PMID 36944972, 2023). "In contrast, HCT116 cells, expressed higher relative levels of CHRM1 mRNA, thus providing us with experimental colon cancer cell lines with a broad range of relative expression of CHRM1 and CHRM3 for our studies." (PMID 37835460, 2023). "Collectively, these findings define efficacious bile acid concentrations, emphasize the importance of co-expression of CHRM3 and EGFR for bile acid-induced colon cancer cell proliferation, and identify the key role of post-EGFR ERK signaling." (PMID 24212649, 2011). "Determining expression levels of both CHRM3 and EGFR in tumor tissue obtained from individuals with colon cancer might enlighten in vivo reflections and importance of our results." (PMID 36919835, 2023). "We examined the relationship between CHRM3/M3R and ARHGEF7/βPix expression in colon cancer." (PMID 37805544, 2023). "CHRM3 and ARHGEF7 are in the top 10% overexpressed colon cancer genes." (PMID 37805544, 2023). "To explore the relative expression of M1R and M3R in established human colon cancer cells, we selected three commonly used cell lines to examine the relative expression of CHRM1 and CHRM3 mRNA; HT-29, H508, and HCT116 cells were used in many of our in vitro studies of colon cancer cell function." (PMID 37835460, 2023). "On the other hand, cell proliferation was not stimulated by BAs in CHO colon cancer cells that express only CHRM3 and SNU-C4 cells that express only EGFR." (PMID 36919835, 2023). "We reasoned that genes whose expression levels were different in tumors from Chrm3-/- compared to WT mice, but not in tumors from Chrm1-/- compared to WT mice, would more likely be relevant to M3R-induced colon tumor promotion." (PMID 24694019, 2014).
colon cancer (continued). "In addition to demonstrating that CHRM3/M3R and ARHGEF7/βPix are coordinately overexpressed in colon cancer, immunoprecipitation experiments revealed that in the cytosol and nucleus M3R activation provokes time-dependent βPix binding to β-catenin by a PKC-dependent mechanism." (PMID 37805544, 2023). "We also confirmed the absence of compensatory increases in Chrm3 expression in Chrm1-/- mice that could account for the Chrm1-/- colon tumor phenotype." (PMID 24694019, 2014). "No such changes were observed in a colon cancer cell line (SNU-C4) that does not express CHRM3." (PMID 24212649, 2011). "Whereas, in azoxymethane-treated mice, ablating CHRM3 expression attenuates colon neoplasia, ablating CHRM1 did not significantly alter colon tumor number or size and, surprisingly, may have trended towards promoting colon neoplasia." (PMID 33450835, 2021). "Here, to explore the individual roles and interplay between two muscarinic receptor subtypes, we analyzed systematically the effects of Chrm3 and Chrm1 gene ablation, alone and in combination, on AOM-induced murine colon neoplasia, a model closely resembling non-hereditary human colon cancer." (PMID 24694019, 2014).
prostate carcinoma (10 papers, 2017 to 2024). A carcinoma that arises from epithelial cells of the prostate gland. "CHRM3 is known to be upregulated in human prostate cancer samples, and experiments in vivo and in vitro have implicated the autocrine mechanism in the prostate cancer cells’ proliferative and migratory potential." (PMID 29671777, 2018). "Regarding the modulation of the parasympathetic nervous system, blocking cholinergic receptor muscarinic 3 (CHRM3) by darifenacin inhibited prostate cancer growth in vitro and in vivo." (PMID 39766161, 2024). "Carbachol is a selective CHRM3 agonist, which enhances prostate cancer growth via the CaM/CaMKK-mediated phosphorylation of Akt." (PMID 37347365, 2023). "Blocking CHRM3 by darifenacin treatment inhibits prostate cancer growth and castration resistance in vitro and in vivo." (PMID 37347365, 2023). "Overexpression of CHRM3 or activation of CHRM3 by carbachol promoted cell proliferation, migration, and castration resistance in prostate cancer." (PMID 35203526, 2022). "In the recent study, it has been found that autocrine activation of CHRM3 promotes prostate cancer growth." (PMID 28241745, 2017). "S1PR3 expression level was higher in AA than EA prostate cancer patients whereas GALR1, CHRM3, and NPFFR1 expression level was lower in AA than EA prostate cancer patients." (PMID 36937425, 2023). "The muscarinic acetylcholine receptor (CHRM3), although unknown to be related to TNBC, is a key factor in the development of prostate cancer, bladder cancer, and endometrial carcinoma." (PMID 31690011, 2019). "Since we showed that upregulated NGF cannot increase expression of CHRM1 and CHRM3, this result suggests that NGF–CHRM4 might be a unique signaling pathway involved in neuroendocrine differentiation of prostate cancer that differs from canonical acetylcholine–CHRM pathways." (PMID 33398073, 2021).
asthma (7 papers, 2019 to 2024). "COPD-associated eQTLs target cholinergic pathway genes (e.g., CHRM1 and CHRM3) that have previously been implicated as important susceptibility loci for lung diseases (e.g., asthma and COPD)." (PMID 36574990, 2023). "For example, CHRM3 encodes the muscarinic acetylcholine receptor M3, which is a well-characterized drug target for which many approved drugs exist, including for the treatment of asthma and obstructive lung disease." (PMID 34857823, 2021). "Previous studies demonstrated that sequence variations in the promoter region of the CHRM3 gene may be associated with asthma, atopy and early-onset type 2 diabetes." (PMID 39163289, 2024). "In murine models of COPD and asthma, ChRM3 expression was inhibited by the administration of tiotropium." (PMID 31662808, 2019). "Their work emphasizes targets in the inositol phosphate metabolism pathway and CHRM3, aiming to highlight drugs and compounds in development for COPD and asthma, as well as potential drug repositioning opportunities from other clinical fields." (PMID 39664315, 2024). "Considering a predominant role in regulating airway contractility, CHRM3 is a well-known therapeutic target to relieve bronchoconstriction and AHR in obstructive airway diseases such as asthma and COPD." (PMID 38081868, 2023). "Nevertheless, given the robust increases in CHRM3-driven calcium elevation, phosphorylation of MLC, and ASMC contraction, it is easy to envision the scope of the IL-31RA-CHRM3 axis in inducing AHR in asthma." (PMID 38081868, 2023).
glioma (6 papers, 2022 to 2026). A benign or malignant brain and spinal cord tumor that arises from glial cells (astrocytes, oligodendrocytes, ependymal cells). "We found that HRH1 and CHRM3 were expressed at higher levels in GBM (grade IV) in comparison to lower-grade gliomas (grade II and III), while CHRM1 displayed the opposite trend." (PMID 37760589, 2023). "Electrophysiology may also help determine whether additional receptor subunits beyond CHRM1 and CHRM3 contribute to putative cholinergic glioma synapses." (PMID 40541184, 2025). "The well-established antagonist activity of clemastine against H1R and the inhibitory effects of M1R and M3R signaling on oligodendrocyte differentiation prompted us to determine the expression profiles of these three receptor genes (HRH1, CHRM1, and CHRM3) in gliomas." (PMID 37760589, 2023). "The top 5 main targets of semen strychni for the therapy of glioma were ADRB1, ADRB2, CHRM3, ADRA1A, and ESR1, based on the degree value of the software’s network function analysis." (PMID 41430985, 2025). "Stigmasterol, (S)-stylopine, isobrucine, icaride A, and isostrychnine N-oxide (I), which may act on key targets such as ADRB1, ADRB2, CHRM3, ADRA1A, and ESR1, are the main ingredients of semen strychni used to treat gliomas." (PMID 41430985, 2025). "The core components of semen strychni used in the treatment of glioma included stigmasterol, (S)-stylopine, isobrucine, icaride A, and isostrychnine N-oxide (I), which may operate on core targets such as ADRB1, ADRB2, CHRM3, ADRA1A, and ESR1." (PMID 41430985, 2025). "The identification of a high number of immune processes with the CHRM1, CHRM3 and GRIN-1 neurotransmission-related gene signature may suggest that NT-related gliomas possess distinct tumor immune microenvironments." (PMID 35455749, 2022). "Correlations between the CHRM1, CHRM3 and GRIN-1 NT-1-4 glioma intersecting gene signatures and various immune signaling pathways suggested that NT gliomas may be endowed with distinct tumor immune microenvironments." (PMID 35455749, 2022). "To look into the regulation of specific cellular signaling pathways by neurotransmitter-related genes in glioma, we performed a correlation analysis of the TCGA glioma dataset between previously-identified NT1-4 discriminatory genes (CHRM1, CHRM3 and GRIN1) and non-neurotransmission-related genes." (PMID 35455749, 2022).
colorectal cancer (5 papers, 2015 to 2023). A primary or metastatic malignant neoplasm that affects the colon or rectum. "Based on these considerations, we explored the relationship between reduced expression of CHRM1, increased expression of CHRM3, and the expression levels of genes commonly mutated in colorectal cancer." (PMID 35370785, 2022). "Moreover, CHRM3 activation significantly promotes colorectal cancer invasion via enhanced cellular release of MMP1." (PMID 37744266, 2023). "As recently reported, CHRM3 and post-M3R signaling activation promote cell proliferation via the EGFR/ERK and MAPK pathways in colorectal cancer." (PMID 37744266, 2023).
gastric cancer (5 papers, 2017 to 2026). A primary or metastatic malignant neoplasm involving the stomach. "Mechanistically, vagus nerve‐derived Ach activates Wnt signaling in gastric cancer cells via muscarinic acetylcholine receptor M3 (CHRM3)." (PMID 41556039, 2026). "The data suggest that EGFR is an indispensable molecule in the process of ACh-stimulated gastric cancer cell proliferation; however, the exact mechanism of action between CHRM3 and EGFR is still unclear in gastric cancer." (PMID 41516199, 2025). "Chrm3 was also shown to induce NGF in gastric cancer cells, and the NGF then acts on TrkA receptors in the nearby nerves to facilitate tumor innervation, which is an example of how cholinergic signals promote tumor axonogenesis indirectly." (PMID 32477953, 2020). "For instance, in gastric cancer cells, activated Chrm3 induces Wnt-β-catenin signals downstream of the transcriptional co-activator YAP." (PMID 32477953, 2020). "that CHRM3 is involved in mediating vagus nerve‐induced gastric cancer progression." (PMID 41556039, 2026). "Notably, CHRM3 was overexpressed in human gastric cancer tissue, and correlated with cancer stage and lymph node metastasis." (PMID 41516199, 2025).
prune belly syndrome (5 papers, 2019 to 2023). "AD, MND, and MG were all associated with SNPs in VPS41 (associated with Wilms tumor) and CHRM3 (associated with Eagle-Barrett syndrome)." (PMID 35711735, 2022). "Biallelic variants in CHRM3 are associated with Prune Belly syndrome (OMIM 100100)." (PMID 37288276, 2023). "Indeed, mutations in CHRM3 in humans cause “prune belly syndrome” with combined intestinal and bladder distension." (PMID 34539433, 2021). "Prune belly syndrome due to biallelic variants in CHRM3 is an ultra‐rare disorder." (PMID 31441039, 2019).
schizophrenia (5 papers, 2014 to 2023). A major psychotic disorder characterized by abnormalities in the perception or expression of reality. "In a neural connectivity GWAS in a Chinese schizophrenia case–control sample, CHRM3 variant rs6700381 was significantly associated with abnormal thalamo-orbital FCTX functional connectivity in first-episode schizophrenia patients." (PMID 31740666, 2019). "Furthermore, it was reported that a single nucleotide polymorphism near CHRM3 is associated with functional connectivity abnormalities in treatment-refractory schizophrenia patients." (PMID 37816766, 2023). "CHRM3 may play a vital role in the deficits of the thalamus–cortical connectivities and is associated with schizophrenia dysfunction." (PMID 35203526, 2022). "The protein coded by the upstream gene, CHRM3, is targeted by antipsychotic drugs against schizophrenia and bipolar disorder." (PMID 33087039, 2020). "Taken together, these results show that CHRM3 is strongly co-expressed with GABRG2, HRH3, and CHRNA4 (risk genes for psychotic disorders, epilepsy, and schizophrenia) in THAL and other brain tissues." (PMID 31740666, 2019). "Multiple lines of evidence support the involvement of CHRM3 in schizophrenia, which has some symptoms phenotypically close to Ca-HL." (PMID 31740666, 2019). "In our study, the risk rs115455482*T allele is most significantly associated with lower expression of CHRM3 in THAL, suggesting potential excitatory-to-inhibitory imbalance in the THAL may predispose to cannabis-induced psychosis or schizophrenia." (PMID 31740666, 2019). "On the other hand, the antagonists targeting GABRG-3, GABRG-4, DRD5, ADR -A1D/–B2, CHRM-3, and SLC6A4 (all elevated by FD) are under investigation for treating bipolar disorder and schizophrenia." (PMID 24632812, 2014).
cholinergic urticaria (4 papers, 2015 to 2024). A type of physical urticarias (or hives) that appears when a person is sweating. "We have previously shown that hypohidrosis or anhidrosis associated with cholinergic urticaria is caused by attenuated expression of CHRM3." (PMID 25919462, 2015). "A fourth type (iv) of cholinergic urticaria with acquired anhidrosis and/or hypohidrosis (CholU-Anhd) and reduced cholinergic receptor muscarinic 3 (CHRM3) expression had been demonstrated by colleagues and us." (PMID 38731882, 2024). "In contrast, in the acetylcholine‐directly induced type which is also recognized as Cholinergic Urticaria with anhidrosis/hypohidrosis, eccrine sweat glands lack the expression of CHRM3 receptors thus the expression of CHRM3 is absent in anhidrotic areas and slightly present in hypohydrotic areas." (PMID 37538324, 2023).
colon adenocarcinoma (4 papers, 2014 to 2023). "We found CHRM1 levels were downregulated in colon adenocarcinoma, while, as expected, CHRM3 was upregulated." (PMID 35370785, 2022). "We evaluated the multiplicity of adenocarcinomas per section; 56% of Chrm3-/- mouse colons had no adenocarcinomas and only one Chrm3-/- mouse had more than one colon adenocarcinoma." (PMID 24694019, 2014).
hypohidrosis (4 papers, 2015 to 2024). diminished sweating in response to appropriate stimuli. "In fact, decreased expression of CHRM3 on the epithelial cells of eccrine sweat glands was found in AIGA or CholU with anhidrosis/hypohidrosis." (PMID 34445091, 2021).
adenoma (3 papers, 2014 to 2023). A neoplasm arising from the epithelium. "Previous evidence supporting a functional interaction between MRs and β-catenin signaling consisted of finding fewer and smaller adenomas in the small intestines of ApcMin/+ mice deficient in Chrm3/M3R." (PMID 35370785, 2022). "Moreover, nuclear staining for β-catenin was significantly reduced in adenomas from Chrm3/M3R-deficient ApcMin/+ mice." (PMID 35370785, 2022). "Apoptotic cells were reduced in adenomas from Chrm3-/- and dual KO compared to WT mice (P < 0.01 and < 0.001, respectively)." (PMID 24694019, 2014). "In contrast, Chrm3-/- mice had nearly equivalent numbers of adenomas and adenocarcinomas." (PMID 24694019, 2014). "We collected the resected carcinoma tissues from CRC patients and conducted immunohistochemical (IHC) staining analysis to examine the expression of some representative genes including NEK8, CHRM3, ANO7, B3GNT6, NEURL1, ODC1 and KCNMA1 in colon normal tissue, adenoma tissue and carcinoma tissues." (PMID 36944972, 2023). "Compared to adenomas from AOM-treated WT mice, Ki67 staining was significantly reduced in those from Chrm3-/- and dual KO but not Chrm1-/- mice." (PMID 24694019, 2014).
dementia (3 papers, 2022 to 2024). Loss of intellectual abilities interfering with an individual's social and occupational functions. "Beyond sweating, CHRM3 and ACh-E are important key factors for neurological functions such as REM sleep and adequate cognition, and anticholinergic drugs had been associated with an increased risk of dementia." (PMID 35967390, 2022). "Proteins most highly increased in dementia cases included phospholipid transporter TMEM30A, calcium channel modulator ORAI2, and various muscarinic cholinergic receptors (CHRM1, CHRM3)." (PMID 39107789, 2024).
epilepsy (3 papers, 2011 to 2020). A brain disorder characterized by episodes of abnormally increased neuronal discharge resulting in transient episodes of sensory or motor neurological dysfunction, or psychic dysfunction. "According to GWAS database GRASP21, CHRM3 is an epilepsy risk gene and CHRM3 SNP rs10925980 was nominally associated with genetic generalized epilepsies (P = 1.90 × 10−6) and Ca-HL (P = 0.03) in EAs." (PMID 31740666, 2019). "Moreover, two candidate genes for therapeutic targeting came out from this analysis: SSTR1, a relevant common hub in febrile and afebrile transcriptomes, and CHRM3, due to its putative role in epilepsy susceptibility development." (PMID 22022585, 2011). "The co-expression network analysis permitted to reveal molecular mechanisms underlying the refractory epilepsy phenotypes, pointing out two potential therapeutic targets represented by the genes SSTR1 and CHRM3." (PMID 22022585, 2011).